Y_RNA (Y RNA )
Gene: Miscellaneous RNA gene on chromosome 17 (45,071,442 to 45,071,543, forward strand). Ensembl gene ENSG00000200888.
Homologues: Orthologues: chimpanzee Y_RNA (99% identical), macaque Y_RNA (93% identical). Paralogues in human: RNY3 (92% identical), RNY3P1 (90% identical), Y_RNA (90% identical), Y_RNA (89% identical), Y_RNA (88% identical), RNY3P2 (87% identical), Y_RNA (87% identical), RNY3P7 (86% identical), Y_RNA (86% identical), RNY3P9 (85% identical), Y_RNA (85% identical), RNY3P16 (84% identical), and 97 more.